GPX4 (glutathione peroxidase 4)
Diseases named in the same sentence as GPX4 in open-access papers (continued):
Sharing a sentence is not in itself a finding about the gene and the disease.
cancer (continued). "In other words, GPX4 could help cancer cells evade death by eliminating oxidative stress, subsequently causing progression and poor prognosis." (PMID 36443446, 2022). "Although modulation of ACSL4 may help to sensitize ferroptosis, the situation is usually complicated because the canonical ACSL4 and GPX4-related pathways are vulnerable to the heterogeneity of cancers." (PMID 36517470, 2022). "GPX4 acts as an oncogene and is highly expressed in many malignant tumors." (PMID 36157228, 2022). "Targeting the SIRT6/Keap1/Nrf2/GPX4 signaling pathway facilitates ferroptosis in cancer cells, and this property may be may be one of the potential strategies to address the resistance of cancer cells to sorafenib." (PMID 35847022, 2022). "Another study revealed that circKIF4A could upregulate the levels of GPX4 and reduce the ferroptosis of thyroid cancer cells by sponging miR-1231, and leading to the induction of cancer progression." (PMID 35342359, 2022). "Glutathione peroxidase 4 (GPX4) has been shown to inhibit ferroptosis in cancer cells." (PMID 36211267, 2022). "System xCT is pivotal in the exchange of cystine and glutamate, leading to the synthesis of antioxidant peptide glutathione (GSH) and phospholipid hydroperoxidase glutathione peroxidase 4 (GPX4) activation, eventually protecting cancer cells from lipid ROS attack." (PMID 35884471, 2022). "Finally, we explore how Se influences key selenoproteins in cancer, especially mechanisms related to GPX4-dependent ferroptosis." (PMID 36358931, 2022). "We found that the expression of GPX4 was significantly increased in 13 cancers." (PMID 34975326, 2022). "Furthermore, IPP-derived CoQ can be converted into ubiquinol (CoQH2) by ferroptosis suppressor protein 1 (FSP1) to inhibit lipid peroxidation and ferroptosis, and FSP1 can act in parallel to the GPX4 pathway to inhibit ferroptosis in cancer cells." (PMID 35013137, 2022). "Directly targeting GPX4 may serve as an efficient strategy to induce ferroptosis in cancer cells in vivo and provide a new approach for ROS manipulation-based cancer therapy." (PMID 35105963, 2022). "If this hypothesis can be applied to our results, the poor prognosis of LUAD with GPX4 expression may be due to the suppression of ferroptosis in cancer cells." (PMID 36443446, 2022). "As GPX4 has traditionally been thought of as resistant to limited Se pools, this finding indicates that the selenoprotein hierarchy may be altered in cancer cells, resulting in an overreliance on GPX4." (PMID 36358931, 2022). "GPX4 is elevated in various cancer types where it enhances anti-cancer drug resistance." (PMID 34784264, 2022). "A reason for this GPx4 dependency is that cancer cells rely on iron at a greater level than normal cells for growth, metabolism, and metastasis resulting in iron being available as a catalyst for rapid lipid peroxidation if the lipid membrane is not protected by GPx4." (PMID 36591540, 2022). "In addition, almost all recent findings of PDT-induced ferroptosis are through the canonical ACSL4 and GPX4-related pathways, which are vulnerable to the heterogeneity of cancers." (PMID 36517470, 2022). "GPX4 activity is important for the survival not only of cancer cells but also of immune cells." (PMID 36613888, 2022). "Several anticancer drugs could inhibit ferroptosis-related molecules and channels to induce ferroptosis in cancer cells, such as GPX4 and system Xc-, and then inhibit cancer growth 5,58." (PMID 35342359, 2022). "As we know, GPX4 is an essential regulator of ferroptotic cancer cell death." (PMID 35236309, 2022). "The inactivation of the GPX4 enzyme and the Fe2+-mediated Fenton reaction effectively led to the induction of ferroptosis, synergistically promoting MB-instructed photodynamic tumor therapy by increasing the sensitivity of cancer cells to apoptosis." (PMID 34976215, 2022).
cancer (continued). "In addition, the presence of enzymes that control ferroptosis, such as GPX4, also enables targeted approaches to target ferroptosis to eliminate cancer." (PMID 36338998, 2022). "Indeed, the development of potent small-molecule inducers of ferroptosis, through GPX4 targeting, has been proposed for cancer therapy." (PMID 35158912, 2022). "This adaptive response of GPX4 may promote the survival of cancer cells during radiotherapy, leading to radioresistance." (PMID 35915092, 2022). "Therefore, for this type of cancer cells, the targeted inactivation of the activity of GPX4 by class II and III FINs can induce ferroptosis of the cells." (PMID 34996454, 2022). "However, in cancer cells with high GPX4 levels, inactivation of DHODH exacerbates mitochondrial lipid peroxidation, in concert with ferroptosis inducers." (PMID 36429080, 2022). "In the cancer cells with low expression of GPX4, DHODH markedly protects cells from ferroptosis." (PMID 35882850, 2022). "GPX4 played a role in the induction of cell death in a variety of cancers." (PMID 35574367, 2022). "GPX4 as a cytosolic “peroxidation inhibiting protein” is a specific target of new pharmacological treatments aiming at activating or inhibiting cell death in cancer or degenerative diseases, respectively." (PMID 36613888, 2022). "Mao found that treating cancer cells with GPX4 inhibitors resulted in acute depletion of N-carbamyl-L-aspartate (C-ASP, a pyrimidine biosynthesis intermediate), accompanied by accumulation of uridine, which could be inhibited by fer-1, a ferroptosis inhibitor." (PMID 36309489, 2022). "Various diseases, including cancer, have been linked to abnormal ferroptosis, and inhibition of SLC7A11 and GPX4 may eradicate cancer cell resistant to chemotherapy, targeted therapy or radiotherapy." (PMID 35402284, 2022). "The relationship between GPX4 expression and patient survival outcome depends on the cancer type." (PMID 34996454, 2022). "Our demonstration that sensitivity to GPX4 inhibitors is correlated with NUAK2 expression across numerous cancer cell types suggests that NUAK2 expression may be a potent predictor of vulnerability to GPX4 inhibition." (PMID 35523770, 2022). "The effect of the classic cystine/GSH/GPX4 system on regulating ferroptosis is undeniable, but the sensitivity of diverse cancer cell lines to GPX4 inhibitors is inconsistent, indicating that other regulatory signaling pathways parallel to GPX4 are involved in the process of ferroptosis." (PMID 36238649, 2022). "In addition to the direct or indirect blockage of GPX4 by ferroptosis-inducing compounds, the inhibition of GPX4 expression by modification in the mevalonate pathway also promotes ferroptosis in cancer cells." (PMID 35805884, 2022). "TIMER analysis of TCGA database revealed that GPX4 is overexpressed in many cancers." (PMID 36371529, 2022). "Different cancer cells were found to have different sensitivities to GPX4 inhibitors, and it was speculated that there were other factors controlling resistance to ferroptosis." (PMID 36246888, 2022). "Additionally, they found that the GPX4 inhibitor RSL3 improves the anti-cancer effects of cisplatin by enhancing ferroptosis in vitro and in vivo." (PMID 35620395, 2022). "Therefore, to induce ferroptosis, it is necessary to prevent the cancer cells to compensate the elevated oxidative stress by inhibiting/degrading the antioxidant protection systems (GPX4, FSP1) and to increase the intracellular iron level." (PMID 35406596, 2022). "A recent study indicates that GPX4 is increased in BC cancer tissues than in the normal control." (PMID 35614944, 2022). "Furthermore, triggering ferroptosis induces death in therapy-resistant cancer due to cancer cells relying on GPx4 for survival." (PMID 36591540, 2022).
cancer (continued). "In conclusion, cancer cells prone to ferroptosis tend to have the following metabolic characteristics, including high levels of PUFAs, overloaded iron pools, and vulnerable GPX4–GSH defenses." (PMID 36317423, 2022). "Furthermore, our data showed that this type of cancer shows great resistance to ferroptosis induction either by cysteine starvation, GPX4 inhibition, or FSP1 inhibition." (PMID 36552620, 2022). "Our work and that of others have shown that the most potent and effective way to induce ferroptosis in PDAC and other types of cancers is either to block cysteine import into the cell, by inhibiting the membrane transporter known as xCT or to block the activity of GPX4 enzyme." (PMID 36552620, 2022). "Therefore, there are some already known strategies to induce ferroptosis through canonic pathways in cancer cells by increasing the intracellular iron levels and targeting GPX4 through several mechanisms." (PMID 35805884, 2022). "However, when co-treated with AuNF probes, the low expression of GPX4 strengthened erastin-induced ferroptosis, and this synergy showed a better effect on inhibiting the proliferation of cancer cells." (PMID 36551145, 2022). "Therefore, the inhibition of GPX4 is a key step in the process of exploring the role that contributes to the ferroptosis of cancer cells." (PMID 36551145, 2022). "Indeed, the research from Weimin Wang and colleagues has shown that the combination of GPX4 inhibitor, cyst(e)inase with PD-L1 blockade, can improve T cell-induced antitumor immunity and ferroptotic death of cancer cells synergistically." (PMID 36482419, 2022). "Methylation of GPX4, NLRP3, and CASP5 were associated with better prognosis in majority of cancers." (PMID 36605187, 2022). "Therefore, cancer cells are more dependent on GPX4, especially following epithelial-to-mesenchymal transition (EMT)." (PMID 35105963, 2022). "Subsequently, cancer cell growth was restrained by inducing GPX4-dependent ferroptosis." (PMID 35647032, 2022). "However, some cancer cells remain resistant to ferroptosis even after GPX4 inhibition, indicating the existence of additional ferroptosis defense mechanisms that deserve further investigation." (PMID 36052168, 2022). "Although GPX4 is a core regulatory protein of ferroptosis, the responses of GPX4 inhibitors in different cancer cell lines are inconsistent, suggesting that other factors may regulate ferroptosis." (PMID 35720113, 2022). "Interestingly, system xc−-mediated cystine uptake promotes GPX4 protein translation in an mTORC1-dependent manner, whereas inhibition of mTORC1 reduces GPX4 production and synergized with ferroptosis induction in cancer cells." (PMID 36282248, 2022). "The relationship between drug tolerance and GPX4 levels appears to be complex and may depend on the cancer type or treatment agents, and merits further exploration." (PMID 35719967, 2022). "Accordingly, cancer cell line sensitivity data analysis revealed that statins are selective inducers of ferroptosis in mesenchymal-type cancer cells that may act by inactivating GPX4." (PMID 33801564, 2021). "Besides, supplementation with the substrate and product of dihydroorotate dehydrogenase (DHODH) attenuated or enhanced the inhibition of ferroptosis induced by GPX4, respectively, especially in cancer cells with low GPX4 expression (GPX4low)." (PMID 34778060, 2021). "Inhibition of GPX4 can also selectively kill cancer cells through induction of ferroptosis." (PMID 34315867, 2021). "Compared with bulk cancer cells, GPX4 was upregulated in esophageal CSCs." (PMID 35053196, 2021). "As GPX4 is absolutely required by the cancer cell to reduce the burden of membrane lipid peroxides, this metabolic switch leaves the cancer cell particularly vulnerable to the accumulation of oxidized membrane lipids and cell death through a mechanism consistent with ferroptosis." (PMID 33208460, 2021).
cancer (continued). "Inhibiting GSH synthesis or targeting GPX4 could provide an alternative approach for radiosensitization, especially considering that certain drug-resistant cancer cells are highly dependent on GPX4 for survival." (PMID 33891303, 2021). "Therefore, given the enrichment of TMEM189 in human cancers and poor clinical benefit with high TMEM189 expression, we propose TMEM189 as a very promising therapeutic target than GPX4 for activating ferroptosis in human cancers." (PMID 33731874, 2021). "GPX4 is an important regulator of ferroptosis for cancer cells." (PMID 33928101, 2021). "Interactions between the rapamycin kinase and GPX4 targets may regulate autophagy-dependent ferroptosis in cancer cells." (PMID 34804371, 2021). "Moreover, recent observations indicated breast and other cancer cells uptake selenium and promote selenocysteine biosynthesis, which, by allowing production of selenoproteins such as GPX4, protects cells against ferroptosis." (PMID 33345387, 2021). "As a second possibility, cancer cells might be more detrimental to GPX4 inhibition because they have a higher level of polyunsaturated fatty acids (PUFAs)." (PMID 33672555, 2021). "However, for HCC, we aim at killing these cancer cells by inducing cell death, so it is beneficial to inhibit GPX4 and then activate ferroptosis." (PMID 34820376, 2021). "AURKA overexpression can also inhibit ferroptosis of cancer cells by inhibiting GPX4." (PMID 34616431, 2021). "We next sought to determine whether mTORC1 inhibition, by decreasing GPX4 protein levels, can sensitize cancer cells to ferroptosis induced by GPX4 inhibitors." (PMID 33707434, 2021). "Lack of SLC7A11 and knockdown of GPX4 have been demonstrated to increase ROS-mediated lipid peroxidation and induce subsequent ferroptosis in even resistant cancer cells, indicating that deficiency in antiferroptotic function enhances cancer cell death." (PMID 35118067, 2021). "However, some cancer cells that expressed a low level of GPX4 strongly confers resistance to ferroptosis, suggesting that additional ferroptosis suppressors are supposed to be existing." (PMID 34485285, 2021). "As xCT-positive cancer cell lines are producing more selenide, they may be more dependent on the end product GPX4 to neutralize selenide-induced oxidative stress." (PMID 33672555, 2021). "Glutathione depletion or glutathione peroxidase 4 inactivation may lead to the metabolic imbalance, thereby inducing ferroptosis of cancer cells." (PMID 33928101, 2021). "In addition, RSL3 and DPI7 can directly inhibit the activity of GPX4 to induce ferroptosis, thus exerting a therapeutic effect on cancer." (PMID 35118077, 2021). "Two ITCs, PEITC and sulforaphane protect cells from ferroptosis via limiting iron accumulation and preventing GPX4 degradation and have been investigated in clinical trials against various diseases ranging from cancer to autism, either alone or in combination with other drugs." (PMID 35118067, 2021). "Various studies have shown that induction of ferroptosis via targeting GPX4 might be a promising strategy for killing cancer cells including the NSCLC." (PMID 34621297, 2021). "Another study reported that the increased expression of GPX4 in cancer tissues might be partly attributed to a lower level of DNA methylation and histone acetylation." (PMID 34568341, 2021). "Emerging evidence proves that activation of ferroptosis by glutathione peroxidase 4 (GPX4) may help cancer cells resist therapy and survive as “persister” cells." (PMID 35006432, 2021). "Furthermore, therapy-resistant mesenchymal cancer cells exhibit a greater reliance on GPX4 activity for survival." (PMID 33854057, 2021). "Currently, discovered proferroptotic compounds mainly spotlight on key elements of redox homeostasis (e.g., system xc- and GPX4) to disrupt the existing redox balance and trigger the ferroptotic cascade in cancers whose growth and survival are highly dependent on the uptake of amino acids." (PMID 35118067, 2021).
cancer (continued). "Specifically, GPx4-regulated ferroptosis participates in cancer initiation and progression." (PMID 34611144, 2021). "GPX4 has been described as an essential regulator of ferroptotic cancer cell death." (PMID 34336668, 2021). "While the function and pharmacologic disruption of wildtype GPX4 have been explored for a range of neurodegenerative diseases and various cancers, our belief is that all new knowledge in these fields can, and will, assist the diagnosis and treatment for future sufferers." (PMID 34688299, 2021). "Furthermore, we demonstrate that specific inhibition of HSF1 overcomes resistance to GPX4 inhibition and significantly increases the sensitivity of resistant cancer cells in vitro and tumors in vivo to ferroptosis." (PMID 34223704, 2021). "In this study, we consider the effects of GA on breast (MDA-MB-231) and melanoma (A375) cancer cell line in presence of low-level laser irradiation and evaluated the apoptosis and ferroptosis by determining the activity of GPX4 and MDA as key enzymes in ferroptosis cell death." (PMID 31956296, 2020). "GPX4 also show variable expression within different types of cancer." (PMID 32596160, 2020). "Furthermore, GPX4 is overexpressed in most cancer cells, and the manipulation of GPX4 function can affect the extent of ferroptosis in cancer cells." (PMID 33024562, 2020). "In 2019, Doll and other scholars discovered that the expression of the mitochondrial associated apoptosis inducing factor 2 (AIFM2) gene could make up for the function of GPX4 in human GPX4 deletion cancer cells." (PMID 32908634, 2020). "GPX4 activity was analyzed in cancer cells treated with low-level laser irradiation and GA." (PMID 31956296, 2020). "Since enhanced GPX4 dependence is an adaptive phenotype shared by several types of cancer in response to different therapies, our work might have universal implications for our understanding of metabolic events that underpin resistance to cancer therapies." (PMID 32577235, 2020). "In addition, GPX4 is an essential regulator of ferroptotic cancer cell death that provides antioxidants to counteract lipid peroxidation and is the only enzyme that reduces lipid hydroperoxides in biofilms." (PMID 33294119, 2020). "However, after a latency period, mice carrying GPX4−/− cancer cells developed tumors that proliferated as quickly as GPX4-expressing parental cancer cells." (PMID 33235217, 2020). "Hereditary leiomyomatosis and renal cell cancer is a rare disease caused by the inactivation of fumarate hydratase in the Krebs cycle, which results in the accumulation of fumarates and the alteration of GPX4 function, thereby increasing the sensitivity of cancer cells to ferroptosis." (PMID 33024562, 2020). "GPx4 can alter the mammalian cell cycle, an important aspect in some cancer therapies." (PMID 32414091, 2020). "Furthermore, after screening 177 cancer cell lines, these researchers found that renal cell carcinomas and diffuse large B cell lymphomas are more sensitive to GPX4-regulated ferroptosis." (PMID 33294126, 2020). "Thus, inhibition of GPx4 can lead to increased cell death, making this a potential target for cancer therapies." (PMID 32414091, 2020). "Recently, regulating mast cell processes has been used in a chemotherapy-based strategy for cancer treatment, and several drugs have been shown to trigger cell ferroptosis by acting on system Xc−, glutathione peroxidase 4 (GPX4), and ferritin degradation through autophagy." (PMID 33294119, 2020). "The recognition that GPX4 plays such an important role in ferroptosis in various cancers suggests that the inhibitors of GPX4 could point the way for cancer treatment." (PMID 33665167, 2020). "In that setting, GPx4 may protect cells and tissues from lipid peroxidation, thereby preventing the initiation of cancer." (PMID 32414091, 2020).